PNPLA2 (patatin like domain 2, triacylglycerol lipase)
Description:
Catalyzes the initial step in triglyceride hydrolysis in adipocyte and non-adipocyte lipid droplets. Exhibits a strong preference for the hydrolysis of long-chain fatty acid esters at the sn-2 position of the glycerol backbone and acts coordinately with LIPE/HLS and DGAT2 within the lipolytic cascade (By similarity). Also possesses acylglycerol transacylase and phospholipase A2 activities. Transfers fatty acid from triglyceride to retinol, hydrolyzes retinylesters, and generates 1,3-diacylglycerol from triglycerides. Regulates adiposome size and may be involved in the degradation of adiposomes. Catalyzes the formation of an ester bond between hydroxy fatty acids and fatty acids derived from triglycerides or diglycerides to generate fatty acid esters of hydroxy fatty acids (FAHFAs) in adipocytes. Acts antagonistically with LDAH in regulation of cellular lipid stores. Inhibits LDAH-stimulated lipid droplet fusion. May play an important role in energy homeostasis (By similarity). May play a role in the response of the organism to starvation, enhancing hydrolysis of triglycerides and providing free fatty acids to other tissues to be oxidized in situations of energy depletion (By similarity).
Synonyms: PEDF-R; TTS2; ATGL; FP17548; desnutrin; TTS-2.2; iPLA2zeta; 1110001C14Rik
Tractability: Antibody: UniProt places it where antibodies can reach, with high confidence; its Gene Ontology location is reachable by antibodies, with high confidence; UniProt predicts a signal peptide or a membrane-spanning region. PROTAC: UniProt records ubiquitination sites on it; ubiquitination databases record sites on it; its protein half-life has been measured; a small molecule that binds it is known.
Target class: Enzyme; Hydrolase
Chemical probes: Atglistatin
Gene: Protein-coding gene on chromosome 11 (818,914 to 825,573, forward strand). Ensembl gene ENSG00000177666.
Subcellular location: Lipid droplet; Cell membrane; Cytoplasm
Subcellular location (Human Protein Atlas): Lipid droplets; Nucleoplasm
Pathways (Reactome):
Metabolism of proteins: Post-translational protein phosphorylation; Regulation of Insulin-like Growth Factor (IGF) transport and uptake by Insulin-like Growth Factor Binding Proteins (IGFBPs)
Gene expression (Transcription): MLL4 and MLL3 complexes regulate expression of PPARG target genes in adipogenesis and hepatic steatosis
Metabolism: Acyl chain remodeling of DAG and TAG
Gene Ontology:
Molecular function: acylglycerol O-acyltransferase activity; diolein transacylation activity; mono-olein transacylation activity; phospholipase A2 activity; protein binding; retinyl-palmitate esterase activity; triacylglycerol lipase activity; lipoprotein lipase activity; hydrolase activity
Biological process: intracellular triglyceride homeostasis; lipid droplet disassembly; lipid droplet fusion; triglyceride catabolic process; acylglycerol acyl-chain remodeling; diacylglycerol biosynthetic process; lipid homeostasis; lipid catabolic process; lipid droplet organization; lipid metabolic process; positive regulation of triglyceride catabolic process; retinol metabolic process
Cellular component: lipid droplet; plasma membrane; cytoplasm; endoplasmic reticulum lumen; endoplasmic reticulum membrane; membrane
Genetic constraint (gnomAD): Loss-of-function variants: 28 observed, 31.43 expected, observed/expected ratio (o/e) 0.89, 90% interval 0.66 to 1.22. The synonymous counts are far from expectation, so gnomAD's model fits this gene poorly and the ratio says little. Missense variants: 768 observed, 620.2 expected, observed/expected ratio (o/e) 1.24, 90% interval 1.17 to 1.31. Synonymous variants: 392 observed, 279.29 expected, observed/expected ratio (o/e) 1.4, 90% interval 1.29 to 1.53.
Gene-disease validity (ClinGen):
ClinGen rates the evidence that PNPLA2 causes each of these diseases.
neutral lipid storage myopathy (autosomal recessive): Definitive.
Homologues: Orthologues: chimpanzee PNPLA2 (97% identical), macaque PNPLA2 (93% identical), dog PNPLA2 (85% identical), mouse Pnpla2 (84% identical), guinea pig PNPLA2 (82% identical), pig PNPLA2 (81% identical), rat Pnpla2 (77% identical), tropical clawed frog pnpla2 (63% identical), zebrafish pnpla2 (56% identical). Paralogues in human: PNPLA3 (35% identical), PNPLA5 (31% identical), PNPLA1 (28% identical), PNPLA4 (18% identical).
Diseases named in the same sentence as PNPLA2 in open-access papers:
PNPLA2 is named in the same sentence as 190 diseases in open-access papers, as found by Europe PMC text mining. Sharing a sentence is not in itself a finding about the gene and the disease. The quoted sentences say what the papers report.
Obesity (137 papers, 2009 to 2026). Accumulation of substantial excess body fat. "PNPLA2 encodes an enzyme involved in the hydrolysis of triglycerides in adipose tissue, and has been related to obesity, a highly comorbid disorder in ADHD." (PMID 36153331, 2022). "PNPLA2-knockout (PNPLA2-KO) mice exhibit mild obesity and die from heart disease after 12 weeks, reflecting their inability to mobilize fatty acids for fuel." (PMID 37212279, 2023). "For example, m6A negatively mediated UCP2 protein expression and positively mediated PNPLA2 protein expression to regulate obesity development." (PMID 32444598, 2020). "Two studies have demonstrated genetic association between PNPLA2 and PNPLA3 with type 2 diabetes and obesity, respectively." (PMID 19390624, 2009). "Similarly, we discover PNPLA2 and PNPLA3, for which genetic variations have previously been associated with obesity and non-alcoholic fatty liver disease, as the key nodes bridging Triglyceride metabolic process cluster with central regulatory mechanisms." (PMID 25466819, 2015). "Pnpla2 (adipose triglyceride lipase (ATGL)) initiates the first step of triglyceride hydrolysis and is a rate-limiting regulator of lipolysis; its deficiency results in lipid accumulation in hearts, obesity, cardiometabolic dysfunction, and impaired thermogenesis." (PMID 41509418, 2025). "BAT ‘whitening’ and decrease of its activity have been described in obesity, during adaptation to thermoneutral conditions, or due to leptin receptor deficiency, β-adrenergic signaling impairment or deficiency of adipose triglyceride lipase (ATGL; officially known as PNPLA2)." (PMID 35466996, 2022). "Concordant with several metabolic traits identified in the PheWAS such as obesity and cholesterol levels, the QTL analyses identified two genes, PNPLA2 and USF1, whose functions are directly connected to those traits." (PMID 34027315, 2021). "On the contrary, three genes involved in angiogenesis and one involved in energy homeostasis were up-regulated in thew SAT of individuals with normal weight compared to individuals with obesity; DLL4, PLIN2, VEGFA and PNPLA2." (PMID 33022994, 2020). "For PNPLA2, common variants has been associated with free fatty acid levels, triglyceride levels and type 2 diabetes suggesting that the gene may play an important role for the risk factors associated with obesity rather than obesity per se." (PMID 19390624, 2009). "Additionally, a direct correlation between BMI and gene expression was observed for AGER, ANGPT2, CD68, IFI30, NOTCH3 and SPP1, whereas an inverse correlation was achieved for DLL4, PLIN, PNPLA2 and VEGF (genes that were down-regulated due to obesity)." (PMID 33022994, 2020). "No variants in the PNPLA2, PNPLA4 and PNPLA5 were associated with obesity in this cohort." (PMID 19390624, 2009). "Contrary to what we could expect from previous studies, the levels of the PNPLA2, gene involved in the maintenance and development of AT, as well as in regulating energy homeostasis, was significantly lower in the SAT of patients with obesity as compared to individuals with normal weight." (PMID 33022994, 2020).
Hepatic steatosis (77 papers, 2011 to 2026). Steatosis is a term used to denote lipid accumulation within hepatocytes. "In contrast, a missense genetic variant in PNPLA3 (I148M) in humans is strongly associated with fatty liver disease by reduced hydrolase activity and disruption of Pnpla2/ATGL function on the lipid droplet surface." (PMID 33013449, 2020). "Next, we observed sporadic fatty liver phenotypes in Q140K+/+ males, but not WT animals and found in the same males altered gene expression in markers of fatty liver disease (Pnpla2, p = 0.012; Pnpla3, p = 0.050; and G6pd, p = 0.032, Student’s t-tests)." (PMID 32488095, 2020). "Driven by the evidence that ATGL is the major enzyme for hepatic TGs hydrolysis and that liver-specific ATGL deficiency causes hepatic steatosis, a contributing risk factor for HCC onset, the expression levels of the PNPLA2 gene (hereinafter referred to as ATGL) were analyzed in human HCC biopsies." (PMID 30367149, 2019). "Interestingly, the present data are the first to show that diet restriction increased expression of Pnpla2– a possible, novel mechanism behind the beneficial effects of diet restriction in alleviating fatty liver." (PMID 24551121, 2014). "Indeed, p.I148M overexpression raised hepatic TG concentrations in wt, but not in Cgi-58 knock-out (KO) mice, indicating that the PNPLA3 mutation may prompt hepatic steatosis, hindering ATGL/PNPLA2 activity on LDs in a CGI-58-dependent manner." (PMID 34680476, 2021).
Insulin resistance (52 papers, 2011 to 2026). Increased resistance towards insulin, that is, diminished effectiveness of insulin in reducing blood glucose levels. "FAHFA, derived from the activity of patatin-like phospholipase domain containing 2 (PNPLA2, also known ATGL), are involved in glucose homeostasis, insulin resistance and anti-inflammatory functions." (PMID 37196109, 2023). "Conversely, downregulating the fatty acid oxidation genes Pnpla2 and Plin2 may promote the formation of intracellular lipid droplets, while downregulating the Irs2 gene may induce insulin resistance and inhibit autophagy in liver cells, ultimately triggering NAFLD." (PMID 37047411, 2023).
steatosis (42 papers, 2012 to 2026). Increased lipid within the cytoplasm of cells. "Disruption of Pnpla2 prevents extraction of free fatty acids from lipid droplets, leading to severe steatosis and hepatic inflammation in mice." (PMID 25733650, 2015). "Importantly, PNPLA3 I148M sequesters ABHD5 away from PNPLA2 leading to steatosis and modifies TAG metabolism in an ABHD5-dependent manner." (PMID 39814233, 2025). "Such limitations are especially relevant when analyzing Plin2 function in the liver, given that Plin5 binds and regulates the activity of ATGL, steatosis is exacerbated in Pnpla2 (ATGL)−/− mice, and as shown in this study, Plin5 is overexpressed in Plin2−/− livers." (PMID 37844775, 2023). "In the liver, genetic ablation of PNPLA2 promotes steatosis." (PMID 35625102, 2022). "Together these data suggest that PNPLA3 I148M targeting and accumulation on LDs is required for initiating steatosis and further support a model by which PNPLA3 I148M sequesters ABHD5 and prevents activation of PNPLA2." (PMID 39814233, 2025). "IRGM is generally localized on endosomes/lysosomes, while in HFD-fed mice it co-localizes with ATGL/PNPLA2 at LD surface, where it recruits autophagic mediators, such as LC3B, in attempt to counteract to steatosis development." (PMID 34680476, 2021). "A model that has been proposed that is consistent with the neomorph hypothesis is that PNPLA3-I148M sequesters CGI-58/ABHD5, a cofactor for the triglyceride hydrolase ATGL/PNPLA2, impairing triglyceride hydrolysis on cytosolic lipid droplets (LDs) and thereby driving steatosis." (PMID 38657050, 2024).
breast carcinoma (31 papers, 2017 to 2026). "Collectively, these findings delineated a significant promotional effect of OLR1 on breast cancer progression, with the darkest color, highest AUC value, and greatest risk, while a notable protective function of PNPLA2." (PMID 40282270, 2025). "In the ebi-a-GCST90018799 cohort, genes with causal relationships to breast cancer included NOP58, OCIAD2, P4HA2, PEMT, and PNPLA2." (PMID 41424847, 2026). "Additionally, previous research has confirmed the roles of these five central genes (CEACAM6, CAMP, PNPLA2, OLR1, and ADIPOR1) in breast cancer, which were consistent with our predictions of risk and protective factors." (PMID 40282270, 2025). "In contrast, the expression levels of PIK3R1, PNPLA2, ATOH8, TTC23, and CWF19L2 were dramatically lower in breast cancer samples than in healthy controls (p < 0.05)." (PMID 40282270, 2025).
Lipid storage disease (30 papers, 2008 to 2026). "Mutations in PNPLA2 can cause Neutral Lipid Storage Disease with Myopathy (OMIM: 610717) which presents with similar symptoms suggesting both disorders share a common pathway via PNPLA2." (PMID 39480826, 2024). "On the contrary, in some neutral lipid storage diseases (NLSDs) in which myopathy can occur, such as the form related to Patatin Like Phospholipase Domain Containing 2 (PNPLA2) gene mutation, the profile of acylcarnitine and carnitine is typically normal." (PMID 38254650, 2023). "The beginning of the 21st century opened with the discovery of the gene sequences, ABHD5 and PNPLA2, whose mutations cause the onset of the two neutral lipid storage diseases." (PMID 30795549, 2019). "PNPLA2 gene mutations cause neutral lipid storage disease with myopathy (NLSD-M) or cardiomyopathies." (PMID 30223778, 2018). "Studies have shown that mutations in PNPLA2 caused neutral lipid storage disease combined with myopathy (NLSDM)." (PMID 29416711, 2018). "To date, five mutations in human PNPLA2/ATGL have been reported that cause neutral lipid storage disease with myopathy." (PMID 18549477, 2008). "PNPLA2 has been linked to neutral lipid storage disease and IMF accumulation." (PMID 40278360, 2025). "Similarly, mutations in the PNPLA2 gene, which encodes ATGL in humans, can lead to neutral lipid storage diseases with myopathy." (PMID 29747466, 2018). "In man, deficiency of PNPLA2/ATGL causes neutral lipid storage disease with myopathy (OMIM 610717)." (PMID 18549477, 2008).
hepatocellular carcinoma (26 papers, 2017 to 2026). A malignant tumor that arises from hepatocytes. "This confirms that the reduced EEF development observed in PNPLA2 knockdown Huh7 hepatoma cells could not be reproduced, both, in MBA-differentiated Pnpla2−/− E14 mouse ESCs, and, NLSDM patient fibroblasts." (PMID 32442532, 2020).
cardiomyopathy (23 papers, 2013 to 2025). A disease of the heart muscle or myocardium proper. "Through the literature review, the ECG and imaging features and the prognosis of 49 previously reported cases of cardiomyopathy caused by the PNPLA2 mutation were summarized." (PMID 39119584, 2024). "Cardiac death or heart transplantation was recorded in 11/51 (21.6%) of patients with cardiomyopathy and the PNPLA2 mutation." (PMID 39119584, 2024). "PNPLA2 mutations can induce severe lipodystrophy, which can lead to severe cardiomyopathy due to an abnormal energy source." (PMID 35886059, 2022). "Cardiomyopathy related to PNPLA2 loss-of-function variants could result in a poor prognosis." (PMID 39119584, 2024). "Our report suggests that for patients with cardiomyopathy accompanied by elevated CK levels, the possibility of neutral lipid storage disease should be considered, and the PNPLA2 gene should be considered for inclusion in cardiomyopathy genetic panels." (PMID 39119584, 2024). "Mutations in either PNPLA2 or ABHD5 gene in humans cause neutral lipid storage disease with myopathy (NLSDM), characterized by systemic accumulation of triglycerides in lipid droplets, which often requires heart transplantation due to severe cardiomyopathy." (PMID 38706718, 2024). "The clinical characteristics, genotype–phenotype correlation, and prognosis of cardiomyopathy secondary to PNPLA2 mutation are not understood." (PMID 39119584, 2024).
Cachexia (19 papers, 2013 to 2024). Severe weight loss, wasting of muscle, loss of appetite, and general debility related to a chronic disease. "Both findings are congruent with the requirements of ATGL and to a lesser extent HSL for adipose wasting in murine models of cancer cachexia in Pnpla2-/- or Lipe-/- genetic backgrounds." (PMID 35785158, 2022). "Furthermore, the specific activation of adipose triglyceride lipase (PNPLA2; also known as ATGL) in the white adipose tissue and skeletal muscle of cancer patients has been linked to cachexia, suggesting that inhibition of lipases might help alleviate the devastating problems associated with it." (PMID 27635066, 2016).
heart failure (18 papers, 2017 to 2025). Inability of the heart to pump blood at an adequate rate to meet tissue metabolic requirements. "The cKO mice live to an advanced age, in contrast to the constitutively silenced PNPLA2-KO mice in which the lack of the gene causes premature lethality (12–16 weeks) due to heart failure associated with massive accumulation of lipids in cardiomyocytes." (PMID 33605986, 2021).
ichthyosis (16 papers, 2010 to 2025). Disorders of cornification that are characterized by visible scaling and/or hyperkeratosis of most or all of the skin. "Our observations resemble the more widespread phenotype of human or murine CGI58 mutations, causing hepatomegaly, hepatosteatosis, and ichthyosis, when compared with the more restricted phenotype of PNPLA2 deficiency." (PMID 37212279, 2023). "Neutral lipid storage disease with myopathy (NLSDM) and with ichthyosis (NLSDI) are rare autosomal recessive disorders caused by mutations in the PNPLA2 and in the ABHD5/CGI58 genes, respectively." (PMID 30795549, 2019). "Structural defects in the PNPLA2 gene mainly lead to myopathic symptoms, whereas mutations in the CGI58 gene, the activator of PNPLA2, mainly cause ichthyosis and hepatic symptoms associated with myopathic symptoms." (PMID 28499397, 2017). "In 2001 and 2007, mutations in CGI-58 (also termed α/β hydrolase domain-containing 5) and ATGL (also termed desnutrin or PNPLA2) were linked to NLSD with ichthyosis and NLSDM, respectively." (PMID 26109679, 2015). "Structural defects of the Patatin Like Phospholipase Domain Containing 2 (PNPLA2) gene mainly cause heart and skeletal muscle symptoms, whereas mutations in CGI58, the activator of PNPLA2, cause also ichthyosis and severe hepatic symptoms, associated with myopathic symptoms." (PMID 30477112, 2018). "The ATGL gene (alias PNPLA2) has been identified as the causative gene for the neutral lipid storage disease with myopathy without ichthyosis (NLSDM)." (PMID 21122093, 2010).
diabetes (15 papers, 2014 to 2025). "In these networks, ATGL (Pnpla2), is a prominent protein of the lipid droplet cluster, and STRING analysis connects this protein to diabetes related pathways including mTOR signaling and amyloid formation." (PMID 39562539, 2024).
type 2 diabetes (15 papers, 2008 to 2025). "In this study, we aimed to evaluate the contribution of PNPLA2 gene polymorphisms to the progression of DKD in patients with type 2 diabetes in a Chinese Han population." (PMID 32685558, 2020). "Second, although the two tagSNPs in PNPLA2 gene were identified as susceptibility variants of DKD in patients with type 2 diabetes in a Chinese Han population, it is important to screen more sites in PNPLA2 gene to clarify the interaction between SNPs and DKD." (PMID 32685558, 2020). "Genetic variations within the human PNPLA2/ATGL gene influence fasting free fatty acid and glucose levels as well as the risk to develop type 2 diabetes." (PMID 18549477, 2008). "In conclusion, our study suggests that A allele of PNPLA2 rs28633403 and G allele of rs1138714 are significantly associated with risk of DKD in patients with type 2 diabetes in a Chinese Han population." (PMID 32685558, 2020). "Our results suggest that PNPLA2 rs28633403 and rs1138714 are significantly associated with the risk of DKD in a Chinese Han population with type 2 diabetes." (PMID 32685558, 2020). "In this article, we demonstrated PNPLA2 rs28633403 and rs1138714 to be significantly associated with DKD in the Chinese Han population with type 2 diabetes." (PMID 32685558, 2020).